PLEK (pleckstrin)
Diseases named in the same sentence as PLEK in open-access papers (continued):
Sharing a sentence is not in itself a finding about the gene and the disease.
centronuclear myopathy (2 papers, 2013 to 2014). Centronuclear myopathy (CNM) is an inherited neuromuscular disorder characterized by clinical features of a congenital myopathy and centrally placed nuclei on muscle biopsy. "For example, in DNM2, mutations giving rise to a centronuclear myopathy phenotype are enriched in the interface between the middle domain and the pleckstrin homology domain, while mutations implicated in Charcot-Marie-Tooth disease tend to cluster in other parts of the pleckstrin homology domain." (PMID 25353622, 2014).
colorectal cancer (2 papers, 2008 to 2014). A primary or metastatic malignant neoplasm that affects the colon or rectum. "Using a statistical framework, we identified four putative cancer genes (RWDD1, NCF1, PLEK, and VAV3), whose expression profiles were associated with overall poor survival rates in melanoma, lung, or colorectal cancer patients." (PMID 25360158, 2014). "We identified four putative cancer genes (RWDD1, NCF1, PLEK, and VAV3), whose gene expression profiles were associated with overall poor survival rates in melanoma, lung, or colorectal cancer patients." (PMID 25360158, 2014).
diabetes (2 papers, 2020 to 2021). "study on diabetes demonstrated that phosphorylation of pleckstrin (a 47-kDa protein) is significantly increased in mononuclear phagocytes from diabetics compared with controls." (PMID 35087525, 2021). "In diabetes, PLEK has been reported to promote the secretion of proinflammatory cytokines such as TNF-α and IL-1β in mononuclear phagocytes; these cytokines have already been linked to increased risk of UC and RA." (PMID 33262784, 2020).
Intellectual disability (2 papers, 2022 to 2024). "Homozygosity of the p.Arg204Trp variation in the Pleckstrin homology and RhoGEF domain containing G2 (PLEKHG2) gene, which encodes a Rho family-specific guanine nucleotide-exchange factor, is responsible for microcephaly with intellectual disability." (PMID 35203342, 2022).
nasal polyps (2 papers, 2021 to 2022). "Among these genes, PLEK was reported to be involved in CRSwNP but not correlated with M2 macrophages while AIF1, CD53 and LAPTM5 were related to M2 macrophages but not explored in nasal polyps." (PMID 36466903, 2022).
Anxiety (1 paper, 2020). Intense feelings of nervousness, tension, or panic often arise in response to interpersonal stresses. "The results evidenced that the double mutation of the PDK1 pleckstrin homology (PH) domain resulted in an enhancement of the negative valence system shown as an increase of responses of fear- and anxiety-like behaviors in anxiogenic situations." (PMID 32457586, 2020).
Chung-Jansen Syndrome (1 paper, 2026).
congenital myasthenic syndrome (1 paper, 2023). Congenital myasthenic syndrome (CMS) is a group of genetic disorders of impaired neuromuscular transmission at the motor endplate characterized by fatigable muscle weakness. "We identified a patient with congenital myasthenic syndrome (CMS) with two heteroallelic mutations in DOK7, c.653-1G>C in intron 5 and c.190G>A predicting p.G64R in the pleckstrin homology domain." (PMID 36579833, 2023).
dementia (1 paper, 2024). Loss of intellectual abilities interfering with an individual's social and occupational functions. "Four protective proteins (PLEK, DAPP1, CSK and CASP3) that decreased postinfection in the BLSA were significantly decreased in dementia cases in the ARIC study, with several other protective proteins (EIF4A1, DSG1, PIK3CG, PRKCB and LYN) showing similar trends." (PMID 39143319, 2024).
hepatocellular carcinoma (1 paper, 2021). A malignant tumor that arises from hepatocytes. "The downstream effectors of class I PI3Ks share a pleckstrin homology (PH) domain and include serine/threonine kinases from the AGC kinase family, tyrosine kinases expressed in hepatocellular carcinoma (HCC, TEC family) and guanine nucleotide exchange factors (GEFs)." (PMID 34916492, 2021).
HIV-1 infection (1 paper, 2024). The type species of lentivirus and the etiologic agent of acquired immunodeficiency syndrome (AIDS). "Investigating the interactions between PLEK, hsa-miR-200a-3p, and HIV-1 may provide new insights into regulatory mechanisms for HIV-1 infection." (PMID 39519306, 2024).
leukemia (1 paper, 2021). A malignant (clonal) hematologic disorder, involving hematopoietic stem cells and characterized by the presence of primitive or atypical myeloid or lymphoid cells in the bone marrow and the blood. "PHLPP2 and pAMPK interact with each other, and the pleckstrin homology (PH) domain on PHLPP2 is required for their interaction, for dephosphorylating and inactivating AMPK, and for the apoptotic response of the leukemia cells to glucose limitation." (PMID 34608126, 2021).
malaria (1 paper, 2016). Malaria is a serious and sometimes fatal disease caused by a parasite that commonly infects a certain type of mosquito which feeds on humans. "Using a combination of bioinformatic analysis and functional studies in the rodent malaria model Plasmodium berghei, we identified a conserved Plasmodium protein PbPH (PBANKA_041720) containing a pleckstrin homology (PH) domain." (PMID 27038925, 2016).
multiple sclerosis (1 paper, 2020). A progressive autoimmune disorder affecting the central nervous system resulting in demyelination. "There are studies that indicate the participation of PLEK in multiple sclerosis, which is a chronic autoimmune demyelinating disease of the central nervous system." (PMID 33120991, 2020).
Noonan syndrome (1 paper, 2018). Noonan Syndrome (NS) is characterized by short stature, typical facial dysmorphism and congenital heart defects. "Noonan syndrome has been reported to be associated with changes in the pleckstrin homology domain structure due to I437L variations." (PMID 30541462, 2018).
osteosarcoma (1 paper, 2025). A usually aggressive malignant bone-forming mesenchymal neoplasm, predominantly affecting adolescents and young adults. "First, among all candidates, PLEK was the only gene consistently upregulated in osteosarcoma tissues at both the mRNA and protein levels, as confirmed by qRT-PCR and Western blotting." (PMID 40895569, 2025). "Consistent with our observations from TCGA and GTEx, most hub genes—including PLEK, CYBB, CXCR4, and ITGAM—were significantly upregulated in osteosarcoma samples compared to normal controls." (PMID 40895569, 2025). "Mechanistically, PLEK may exert its effects through macrophage-derived cytokine signaling pathways, such as the MIF and TNF pathways previously identified as active in macrophage-osteosarcoma cell communication." (PMID 40895569, 2025).
periodontal disease (1 paper, 2021). "The significant upregulation of pleckstrin levels in the presence of IL-1β or LPS in gingival cells further supports a potential role of this protein in the inflammatory response driving periodontal disease progression." (PMID 35087525, 2021).
Proteus syndrome (1 paper, 2023). Proteus syndrome (PS) is a very rare and complex hamartomatous overgrowth disorder characterized by progressive overgrowth of the skeleton, skin, adipose, and central nervous systems.
schizophrenia (1 paper, 2012). A major psychotic disorder characterized by abnormalities in the perception or expression of reality. "Interestingly, it has been shown that MTMR2 requires a Pleckstrin homology-GRAM domain for membrane association, and both MTMR2 and PLEK have been found here to be downregulated in the STG of schizophrenia patients." (PMID 22441714, 2012).
Sleep apnea (1 paper, 2017). An intermittent cessation of airflow at the mouth and nose during sleep is known as sleep apnea. "Suggestive associations of symptoms of sleep apnea were observed with 11 rare variants (located in KANK2, LCN6, TRAF3, PLEK, HIF1A, SLC45A3, ERCC1/CD3EAP, MRGPRE, GRAMD4, TYW5, CST5)." (PMID 29093733, 2017).
Thrombocytopenia (1 paper, 2021). A reduction in the number of circulating thrombocytes. "Pleckstrin-null platelets from a pleckstrin null knockout mouse exhibited a marked defect in granule secretion, aggregation, actin polymerization and mild thrombocytopenia." (PMID 34837956, 2021). "We found eight proteins (ITGA2B, ITGB3, VWF, PLEK, TNF, TLR2, BCL2 and BCL2L1) were the core targets of DMAG for the treatment of thrombocytopenia." (PMID 34837956, 2021).
cancer (17 papers, 2012 to 2025). A tumor composed of atypical neoplastic, often pleomorphic cells that invade other tissues. "It has been established that the E17K mutation in the AKT1 protein’s pleckstrin homology (PH) domain encourages protein phosphorylation and membrane localization, which, in turn, results in cancer." (PMID 38921000, 2024). "The cumulative impact of pleckstrin and their associated genes on various cancers, Gene Ontology (GO), and pathway analyses were used for their evaluation." (PMID 38921000, 2024). "Recently it has been shown that E17K mutation in the Pleckstrin Homology (PH) domain of AKT1 protein leads to cancer by amplifying the phosphorylation and membrane localization of protein." (PMID 23741320, 2013). "Our study of the underlying mechanism of cancer prognosis concerning pleckstrin expression may be aided by the finding that the patterns of PHLDA1, PHLDA2, and PHLDA3 co-expression regulated the clinical outcomes of individuals with certain types of cancer." (PMID 38921000, 2024). "The bar charts show the total alteration frequency of six hub genes (CD36, CXCL12, CXCR4, CYBB, ITGAM, PLEK) in pan-cancer." (PMID 40895569, 2025). "To determine the role of pleckstrin as a prognostic biomarker in human cancers, we conducted a systematic multiomics investigation." (PMID 38921000, 2024). "We also conducted additional research on the mRNA levels of pleckstrin in various cancer types using TCGA data accessed through cBioPortal." (PMID 38921000, 2024). "We utilized SuperNova Green to specifically inactivate the pleckstrin homology domain of phospholipase C-δ1 and to ablate cancer cells in vitro." (PMID 29712573, 2018). "In the present study, we aim to target the pleckstrin homology (PH) domain of GAB1 for cancer treatment." (PMID 25569504, 2015). "To identify human cancers with CNAs and pleckstrin gene alterations, we employed cBioPortal." (PMID 38921000, 2024). "Taken together, these seemingly contradicting results suggest that PLEK and ZEB2 may show anti- or pro-tumor effects under different conditions which could be related to gene mutations and different cancer subtypes." (PMID 36969247, 2023). "Pleckstrin, PPI, and co-expression analysis may also be used to predict the probable underlying signaling processes related to the role of PHLDA family members in particular cancers." (PMID 38921000, 2024). "Therefore, our results indicated that a high expression of PLEK may play a protective role in NSCLC cancer, which is in contrast to previous findings." (PMID 36969247, 2023). "We performed correlation analysis of these six genes (PTPRC, TLR8, PLEK, NCKAP1L, RGS18 and CLEC12A) with GPR141 in pan-cancer." (PMID 40959105, 2025). "In pan-cancer, the expression levels of PTPRC, TLRB, PLEK, NCKAP1L, PGS18 and CLEC12A were positively correlated with GPR141." (PMID 40959105, 2025). "The results showed that PTPRC, TLR8, PLEK, NCKAP1L, RGS18 and CLEC12A displayed strong correlation with GPR141 in most cancer types." (PMID 40959105, 2025). "Previously we identified pleckstrin homology (PH) binding domains within PAR1,2&4 as critical sites for cancer-growth." (PMID 38275417, 2024). "Pleckstrin homology (PH) domain leucine-rich repeat protein phosphatase 2 (PHLPP2) is a critical regulator of cellular homeostasis and acts as a tumor suppressor in multiple human cancers." (PMID 35281874, 2022).
tumor (16 papers, 2014 to 2025). "PLEK expression in tumor-infiltrating macrophages is associated with favorable prognosis, increased immune infiltration, and a metabolically active TME that suppresses OS malignancy." (PMID 40895569, 2025). "The product of this pleckstrin homology domain gene, also known as LL5β, is a protein implicated in migration and tumour cell invasion, by stabilizing of the protrusive activity at the cell front." (PMID 26705709, 2016). "This allowed us to conduct a controlled assessment of PLEK function in a tumor-supportive cytokine environment." (PMID 40895569, 2025). "Here, we present the first comprehensive evidence that PLEK expression in tumor-infiltrating macrophages contributes to anti-tumor immunity in OS, potentially by reprogramming metabolic and signaling networks within the TME." (PMID 40895569, 2025). "Although pleckstrin family members such as PLEK2 and CNK1 have been implicated in tumor progression through PI3K-Akt signaling and KRAS-mediated immune modulation, the role of classical PLEK (Plek1) in solid tumors remains largely unexplored." (PMID 40895569, 2025). "Functional assays confirmed that PLEK knockdown in macrophages enhanced OS cell proliferation, migration, invasion, and clonogenic potential, underscoring its tumor-suppressive function via macrophage-mediated crosstalk." (PMID 40895569, 2025). "The enrichment of PLEK in metabolically active macrophages, together with the observation that PLEK expression was associated with reduced OS cell proliferation, migration, and invasion, suggests that these macrophages may play a supportive role in anti-tumor responses." (PMID 40895569, 2025). "Single-cell transcriptomic analysis revealed that PLEK is predominantly expressed in a subset of tumor-infiltrating macrophages with elevated metabolic signatures, including increased glycolysis and oxidative phosphorylation." (PMID 40895569, 2025). "PIT-1, a small molecule PIP3 antagonist (PIT) that blocks pleckstrin homology (PH) domain interaction, including activation of Akt, significantly inhibits tumor angiogenesis and metastasis." (PMID 36344496, 2022). "Finally, PLEK was positively correlated with all immune cell types, highlighting its potential role in shaping the tumor immune landscape." (PMID 40895569, 2025). "Our findings that PLEK expression marks metabolically active macrophage clusters and suppresses OS malignancy suggest a novel role for PLEK in regulating immune cell metabolism to sustain anti-tumor immunity." (PMID 40895569, 2025). "Functional in vitro assays confirm PLEK’s tumor-suppressive role in macrophage–OS interactions." (PMID 40895569, 2025). "Importantly, this study provides functional evidence that disrupting PLEK expression in OS cells enhances the tumor-promoting effects of macrophage-derived paracrine signals." (PMID 40895569, 2025). "By regulating both macrophage metabolism and immune activation, PLEK may serve as a molecular switch that reshapes the TME from a tumor-permissive to a tumor-restrictive state." (PMID 40895569, 2025). "Fourth, PLEK was enriched within metabolically active macrophage clusters characterized by elevated glycolytic and oxidative phosphorylation signatures, linking it directly to the metabolic axis of the tumor microenvironment—a key focus of this study." (PMID 40895569, 2025). "The observed enhancement of OS malignancy following PLEK knockdown may be attributed, at least in part, to dysregulation of these signaling pathways and the resulting shift in macrophage function toward a tumor-promoting phenotype." (PMID 40895569, 2025). "In addition, a recent bioinformatic study indicated that a structure-based approach to target the pleckstrin homology (PH) domain of Gab1 represents a potential tumor-specific cytotoxicity against MDA-MB-231 and T47D BCa cell lines in vitro." (PMID 30665442, 2019). "Both numbers and volumes of tumor nodules in PLEK-KO cells were increased." (PMID 29531808, 2018).
tumor (continued). "In C3, there was a high enrichment of genes that drive tumor cell proliferation and migration, notably C-X-C Motif Chemokine Ligand 8 (CXCL8) and pleckstrin (PLEK)." (PMID 40725006, 2025). "The results suggested that CD4, CD53, EVI2b, PLEK, and SASH3 correlated with tumor purity, immune score, CD8+ T cells, and clinical phenotypes." (PMID 34234827, 2021). "Five coexpressed genes (CD4, CD53, EVI2B, PLEK, and SASH3) were identified as tumor purity coexpressed genes that negatively correlated with tumor purity." (PMID 34234827, 2021). "Among them, CYBB, ITGAM, and PLEK showed significantly negative correlations with tumor purity (ρ = -0.555, -0.514, and -0.44), suggesting their potential as markers of the immune microenvironment." (PMID 40895569, 2025). "A total of 10 structural domains were enriched in the comparison of groups B and A. Pleckstrin homology-like domains, which primarily have multiple biological functions in the cell, particularly in the regulation of cell death and tumor suppression, were not significantly enriched." (PMID 41153443, 2025). "Interestingly, the pleckstrin homology domain interacting with these proteins promoted degradation of HIF-1α independent of oxygen concentration and suppressed tumor progression." (PMID 25361009, 2014).
infection (4 papers, 2012 to 2024). The state of being infected such as from the introduction of a foreign agent such as serum, vaccine, antigenic substance or organism. "The results suggested that multiple plasma membrane proteins may be degraded during infection, in particular proteins that include a pleckstrin homology (PLEKH) domain (for example PLEKHA5) or that function in cell-to-cell adhesion." (PMID 30122656, 2018). "The three most highly upregulated genes in the conjunctiva in response to infection were integrin subunit alpha X (ITGAX), myeloid cell nuclear differentiation antigen (MNDA) and pleckstrin (PLEK) triggering." (PMID 38694515, 2024).
neurodegenerative disease (1 paper, 2025). A disorder of the central nervous system characterized by gradual and progressive loss of neural tissue and neurologic function. "Pleckstrin homology (PH) domain leucine-rich repeat protein phosphatases (PHLPP) has been associated with several neurodegenerative diseases, however, few studies have investigated the role of PHLPP in Parkinson’s disease (PD)." (PMID 41024062, 2025).
PLEK also shares sentences with these, for which no sentence is quoted: ulcerative colitis (4 papers); cardiovascular diseases (3); glioma (3); melanoma (2); prostate carcinoma (2); aneurysm (1); Charcot-Marie-Tooth disease (1); chronic periodontitis (1); Down syndrome (1); Encephalopathy (1); endometrial carcinoma (1); influenza (1); kidney cancer (1); lung squamous cell carcinoma (1); microcephaly (1); multiple endocrine neoplasia type 2A (1); myasthenia gravis (1); myelofibrosis (1); myocardial infarction (1); neuroblastoma (1); non-alcoholic fatty liver disease (1); preeclampsia (1); skin cancer (1); spinocerebellar ataxia (1); trichoepithelioma (1); type 2 diabetes (1); venous thromboembolism (1); viral infection (1).